TIGIT (T cell immunoreceptor with Ig and ITIM domains)
Diseases named in the same sentence as TIGIT in open-access papers (continued):
Sharing a sentence is not in itself a finding about the gene and the disease.
myeloma (continued). "Anti-TIGIT monoclonal antibody decreased myeloma cells in bone marrow and prolonged survival compared with control-Ig or anti-PD-1 monoclonal antibody-treated mice, suggesting that TIGIT expression is more dominant than PD-1 in the immunosuppressive function in MM." (PMID 31842518, 2019). "Whether NK cells with high TIGIT levels promote or inhibit myeloma growth is controversial." (PMID 38410372, 2024). "We also observed that the inhibitory checkpoint receptor TIGIT is more frequently expressed by BM CD8+ T-cells from myeloma patients than PD-1 and CTLA-4, which supports the hypothesis that TIGIT may play a central role in the immune escape of the malignant plasma cells." (PMID 36131131, 2022). "Similarly, high TIGIT expression promoted T cells exhaustion, leading to myeloma progression." (PMID 36605439, 2022). "Currently, nine human anti-TIGIT mAbs are being tested in 43 phase 1/2/3 clinical trials either as a monotherapy or, in most studies, in combination with anti-PD-1/PD-L1 antibodies or chemotherapies for the treatment of advanced solid tumors, and in two trials in multiple myeloma." (PMID 34367161, 2021). "The microbiome stimulates protumorigenic IL32 expression in multiple myeloma (MM) cells via TLRs-NFkB, and Treg-derived IL32 promotes bladder cancer metastasis and immunosuppression together with TIGIT." (PMID 38343549, 2024). "Several monoclonal antibodies targeting TIGIT have been synthesized (iragolumab, AB-154, BMS-986,207, MK-7684) and clinical trials on TIGIT inhibition in several cancer types (e.g., multiple myeloma and chronic myeloid leukemia) have been launched." (PMID 35804863, 2022). "For example, blockade of the immune checkpoints PD-1, CTLA-4, and TIGIT has reported remarkable success in AML, lymphoma, MDS, and multiple myeloma." (PMID 32903786, 2020). "Through co‐culture experiments with activated T cells, we found that overexpression of SEI1 in myeloma cells can significantly inhibit the killing efficiency of activated T cells and promote the expression of T‐cell exhaustion markers (TOX, TIGIT, and TIM3)." (PMID 40135791, 2025). "Collectively, these findings identify TIGIT as a critical regulator of resistance to BCMA-CAR-T therapy and highlight TIGIT blockade as a promising strategy to enhance CAR-T efficacy and overcome relapse in multiple myeloma." (PMID 41419632, 2025). "Furthermore, in the Tim3+PD-1+ CD8 T cells, two inhibitory molecules, TIGIT- and LAG3- double-positive cells were increased by myeloma transplantation and the increment was cancelled by cDC1 depletion." (PMID 39474418, 2024). "Inhibiting TIGIT/CD155 signaling has shown promise in reversing the exhaustion of CD8+ T cells and boosting the effectiveness of anti-tumor treatments in both cervical cancer and multiple myeloma." (PMID 38785789, 2024). "Furthermore, TIGIT-expressing CD4+ T cells represent a tumor-supportive T cell subset in CLL and TIGIT blockade can restore CD8+ T-cell immunity against multiple myeloma (MM)." (PMID 38229100, 2024). "Furthermore, in a study showing the importance of NK cell dysfunction in multiple myeloma, ICOS expression levels were found to be higher in bone marrow CD56bright NK cells from relapsed/refractory patients, while TIGIT and TIM3 were increased." (PMID 39201462, 2024). "Consistent with this, inhibition of TIGIT reduced myeloma progression in transplant and nontransplant experimental systems." (PMID 36512425, 2023). "A phase I/II randomized trial in 2019 in patients with relapsed refractory multiple myeloma is designed to evaluate two agents, anti-LAG-3 and anti-TIGIT, for their immune effects and safety as single agents and in combination with pomalidomide and dexamethasone." (PMID 38017516, 2023). "Notably, TIGIT inhibition induces a reduction in tumor burden, prolonged survival in preclinical Vk*MYC MM models and prevents immune escape in myeloma murine models undergoing stem cell transplant." (PMID 38213954, 2023).
myeloma (continued). "In addition, increasing frequency of TIGIT on CD8+ T cells was reported in mice models of newly diagnosed and relapsed multiple myeloma, which positively correlated with tumor burden." (PMID 36605439, 2022). "T-cell immunoglobulin and ITIM domains (TIGIT) is an inhibitory molecule expressed by lymphocytes that competes with the activating receptor DNAX accessory molecule-1 (DNAM-1) for binding to CD155 and CD112, which is expressed by myeloma cells and other cell types." (PMID 36131131, 2022). "Although our results showed an upregulation of genes associated to cytotoxicity in the BM of patients with SMM compared to MGUS, we also found overexpression of inhibitory molecules such as LAG-3, TIGIT and IDO1, which may affect the anti-myeloma immune response in SMM." (PMID 34880879, 2021). "However, we also found overexpression of inhibitory molecules such as LAG-3, TIGIT and IDO1, which may affect the anti-myeloma immune response in SMM." (PMID 34880879, 2021). "In addition, it is known that CD8+ T cells from myeloma patients co-express other immune checkpoints, such as LAG-3, TIM-3, CTLA4, and TIGIT suggesting multiple pathways limiting T-cell responses at this stage of disease and thus explaining the lack of effect from PD-L1/PD-1 blockade as monotherapy." (PMID 33488620, 2020). "PD-1, TIGIT, TIM3, and LAG3 expression by MFI was not significantly different between HD and late relapsed multiple myeloma CAR T-cell products." (PMID 36874402, 2022). "The key issue we also need to consider is that TIGIT binds to CD112 and CD113 ligands, in addition to CD155 ligands, on the surface of myeloma cells, but our experiments did not observe significant changes in the expression of the remaining ligands after EZH2 inhibitor treatment." (PMID 37239949, 2023).
gastric cancer (44 papers, 2019 to 2026). A primary or metastatic malignant neoplasm involving the stomach. "When compared to TIGIT− CD8+ T cells isolated from gastric cancer patients, functionally exhausted, glycolytically deficient TIGIT+ CD8+ T cells exhibited reduced expression of the GLUT1 glucose importer and the hexokinase 1/2 glycolysis‐initiating enzymes." (PMID 32508018, 2020). "The high expression of TIGIT on CD8+T cells in patients undergoing chemotherapy is closely associated with the recurrence of gastric cancer, and blocking TIGIT could enhance the proliferation capacity of CD8+T cells and induce the secretion of IFN-γ." (PMID 35433470, 2022). "A previous study in gastric cancer patients demonstrated that TIGIT/CD155 signaling downregulates the PI3K-Akt-mTOR pathway in CD8+ T cells, leading to CD8+ T cell exhaustion." (PMID 39918313, 2025). "Lastly, BAX showed positive correlations with several immune inhibitors, including PDCD1 and TIGIT in gastric cancer." (PMID 40652278, 2025). "In summary, our findings indicate that gastric cancer cells inhibit the PI3K/AKT/mTOR pathway in CD8 + T cells by upregulating TIGIT expression on CD8 + T cells." (PMID 38216949, 2024). "In summary, we identified that TIGIT inhibition had different effects across two metastatic gastric cancers from the same patient." (PMID 38008725, 2023). "As part of this study, we confirmed GITR and TIGIT protein expression in a series of colorectal and gastric cancers and confirmed the expression of GITR and TIGIT from independent data sets." (PMID 38008725, 2023). "The role of epigenetics in TIGIT expression and immunotherapeutic sensitivity was also uncovered in gastric cancer." (PMID 35656508, 2022). "For instance, CD155 expressed in gastric cancer cells interacts with TIGIT, resulting in inhibition of glucose uptake and impaired T cell effector function." (PMID 36569893, 2022). "CD8+ T cells in gastric cancer highly express TIGIT, which blocks the metabolic pathway of CD8+ T cells." (PMID 36569893, 2022). "A study based on clinical samples showed that the elevated expression of TIGIT and CD155 in gastric cancer tissues was closely associated with poor prognosis of patients and functional exhaustion of highly infiltrated CD8+T cells." (PMID 35433470, 2022). "It has been reported that the combined expression level of CD155 and TIGIT correlates with the prognosis of lung adenocarcinoma, gastric cancer, hepatocellular carcinoma, and head and neck squamous cell carcinoma." (PMID 35324958, 2022). "In particular, TIGIT overexpression is observed in several malignant tumors, including gastric cancer, noninvasive ductal carcinoma, and melanoma." (PMID 35324958, 2022). "A recent study showed that the percentage of CD8 T-cells that were TIGIT+ increased in gastric cancer patients compared to healthy individuals." (PMID 35008385, 2022). "A recent study demonstrated that the infiltrated CD8+ T cells up-regulated the level of TIGIT in gastric cancer, exhibiting exhausted and decreased metabolic activity." (PMID 35433470, 2022). "The high expression of TIGIT inhibits the antitumor function of CD8 T cells in the microenvironment of gastric cancer." (PMID 33575321, 2021). "As one of the key proteins regulating CD8+ T cells, CD155 can inhibit the metabolism of CD8+ T cells through the TIGIT signaling pathway in gastric cancer 29 and inhibit the immune response by inhibiting the function of CD8+ T cell effectors." (PMID 33994860, 2021). "They found that the proportion of CD8+ T cells expressing TIGIT on the surface of gastric cancer patients increased." (PMID 33117713, 2020). "Other tumour types with conspicuously high densities of TIGIT+ lymphocytes included, for example, intestinal type stomach cancer and squamous cell cancers of various origins." (PMID 30733837, 2019).
gastric cancer (continued). "The research results indicated that there exists a significant positive correlation between DLX2 and CTLA4, PDCD1, HAVCR2 and TIGIT, which may contribute to the gastric cancer cells’ ability to evade immune system attacks." (PMID 41244921, 2025). "Furthermore, the presence of TIGIT expression on CD8 + T cells within peripheral blood mononuclear cells (PBMCs) obtained from gastric cancer patients is correlated with decreased overall survival." (PMID 38216949, 2024). "Increased TIGIT expression in gastric cancer appears to be a favorable event." (PMID 35656508, 2022). "The study of anti-TIGIT inhibitors in gastric cancer treatment is in its infancy." (PMID 36042469, 2022). "Recently, TIGIT expression has been intensively examined in malignant tumors of many organs: skin melanoma, Hodgkin’s lymphoma, hepatocellular carcinoma, glioblastoma, and gastric cancer." (PMID 35971106, 2022). "In gastric cancer patients, TIGIT and PD-1 were found to be upregulated on infiltrating CD8+ T cells in tumor tissues, suggesting that TIGIT may serve as an emerging biomarker." (PMID 36159789, 2022). "In the case of gastric cancer, as in pancreatic ductal adenocarcinoma (PDAC), the CD155/TIGIT axis was identified as a potential therapeutic target." (PMID 36980196, 2023). "High THSD7A expression suppressed the sensitivity of patients with gastric cancer to drugs, such as 5-fluorouracil, bleomycin, and cisplatin, and upregulated immune checkpoints, such as HAVCR2, PDCD1LG2, TIGIT, and CTLA4." (PMID 37905960, 2023). "The immune checkpoint analysis indicated that gastric cancer patients with upregulated GGT5 expression showed a higher TIDE score and expression of CD274, CTLA4, HAVCR2, LAG3, PDCD1, PDCD1LG2, and TIGIT than patients in the GGT5-low expression group." (PMID 35368661, 2022). "Other inhibitors or agonists of immune checkpoint molecules, including the inhibitors of CTLA4, LAG3, Tim3, and TIGIT, as well as the agonists of OX40, are currently in clinical trials in the treatment of gastric cancer." (PMID 36042469, 2022). "TIGIT and PD-1 exerted inhabitation function on CD8+T cell growth, proliferation, and cytokine secretion in gastric cancer patients receiving WT1-targeted DC vaccine." (PMID 35433470, 2022). "Co-culture of gastric cancer cells with CD8+ T cells induces TIGIT expression and metabolic impairment, while the blockade of the TIGIT/CD155 axis restores normal metabolic functions in T cells and promotes antitumor immune response." (PMID 36713558, 2022). "TIGIT inhibition improved CD8 T-cell activation and prognosis in gastric cancer." (PMID 37568192, 2023). "The TIGIT/CD155 axis has been shown to play a role in the immune escape and cancer progression of pancreatic cancer, ovarian cancer, breast cancer, and gastric cancer." (PMID 37109579, 2023). "TIGIT is elevated in gastric cancer patients, where it may regulate the metabolic immune efficacy of CD8+ T cells, and the synergistic blockade of TIGIT and programmed death receptor-1 (PD-1) promoted the immune efficacy of CD8+ T cells." (PMID 35770416, 2023). "In addition, therapeutic strategies targeting other molecules, such as CTLA4, LAG3, Tim3, TIGIT, and OX40, have also been developed to improve the treatment efficacy of gastric cancer immunotherapy." (PMID 36042469, 2022). "TIGIT is overexpressed in many solid tumors, including in liver cancer, colorectal cancer (CRC), breast cancer, thyroid cancer, lung cancer, gastric cancer (GC), esophageal squamous cell carcinoma (ESCC), and melanoma." (PMID 34888386, 2021). "Furthermore, TIGIT and/or PD-1 expression in CD8+T cells is increased in patients with gastric cancer relapse after treatment with SOX (S-1 and oxaliplatin) regimen, whereas no notable increase in the proportion of TIGIT+ and/or PD-1+CD8+T cells was found in relapse-free patients." (PMID 33670993, 2021). "Thus TIGIT/CD155 may be a potential therapeutic target and prognostic marker for gastric cancer." (PMID 35433470, 2022).
hepatocellular carcinoma (43 papers, 2019 to 2026). A malignant tumor that arises from hepatocytes. "TIGIT has diverse roles in HBV-associated hepatocellular carcinoma (HCC) development and progression." (PMID 38592036, 2024). "A study on hepatocellular carcinoma found that TIM-3+ TIGIT+ CD8+ T cells were associated with the rate of progression and poor prognosis of patients with hepatocellular carcinoma." (PMID 36913701, 2023). "TAM-T cell interaction via TIGIT-NECTIN2 has been linked to immunosuppression in hepatocellular carcinoma." (PMID 35538548, 2022). "Increase in the proportion of highly suppressive tumor-infiltrating Treg cells following TIGIT expression is associated with poor clinical outcomes in patients with hepatocellular carcinoma (HCC) and metastatic melanoma." (PMID 33670993, 2021). "Emerging studies highlight its immunosuppressive effects on CD8+ T cells via the CD155/TIGIT signaling pathway in hepatocellular carcinoma, indicating that TIGIT-expressing T cells exhibit compromised functioning against tumors." (PMID 39944754, 2024). "For instance, elevated co-expression of TIGIT and T cell immunoglobulin and mucin-domain-containing-3 (TIM-3), on NK cells was found in patients with hepatitis B virus-associated hepatocellular carcinoma (HBV-HCC)." (PMID 38229100, 2024). "Similar to CD56bright pbNK cells that were co-cultured with hepatoma cells, CD56bright pbNK cells that migrated towards primary hepatocyte organoids preferentially upregulated TIGIT expression." (PMID 36845105, 2023). "In conclusion, we demonstrated that PD1 + TIM3+/T, TIGIT + T/T, and IL-6 levels after immunotherapy can serve as predictors of efficacy in patients with hepatocellular carcinoma." (PMID 38110467, 2023). "It has been found that TIGIT can contribute to the progression of hepatocellular carcinoma by modulating the immunosuppressive effect of cytokines produced by CD155 on CD8 T cells." (PMID 34869039, 2021). "TIGIT+ NK cells are found in human hepatocellular carcinoma, human colorectal cancer, and a number of murine tumor models, including breast cancer (4T1), melanoma (B16), colon cancer (CT26), and MCA-induced fibrosarcoma." (PMID 33613552, 2020). "The levels of PD1 + TIM3 + T/T, TIGIT + T/T, and IL-6 after 2 cycles of immunotherapy may serve as predictors of treatment efficacy in patients with hepatocellular carcinoma." (PMID 38110467, 2023). "Furthermore, a reduced proportion of TIGIT+ NK cells has been observed in the intratumoral region of hepatocellular carcinoma compared to the peritumoral region." (PMID 31681269, 2019). "Hepatocellular carcinoma (HCC) is a major global health concern, and emerging evidence suggests that TIGIT and NKG2A are potential immune checkpoints with implications for HCC progression." (PMID 39540362, 2024). "Moreover, TIGIT blockers synergistically inhibited carcinoma growth when combined with PD-1 inhibitors, suggesting that elevated expression of TIGIT may promote the progression of hepatocellular carcinoma." (PMID 38110467, 2023). "Importantly, co-culture with PVR-expressing human hepatoma cells or primary hepatocyte organoids enhanced TIGIT expression and reduced DNAM-1 expression on CD56bright pbNK cells, suggesting a potential influence of the liver environment on the phenotype and function of ihNK cells." (PMID 36845105, 2023). "Hepatocellular carcinoma cells increase the expression of PVRL1, which suppresses cytotoxic T-cell activity through TIGIT, thereby promoting tumor resistance to PD1 inhibitors." (PMID 40612112, 2025). "A recent study found that a subset of CD112-expressing DCs in the TME of human hepatocellular carcinoma interact with NK cells through CD226 and TIGIT." (PMID 33613552, 2020). "Moreover, a recent study performed in HBsAg-transgenic (tg) mice upon TIGIT-inhibition showed that therapeutic HBsAg vaccination further induced inflammation and hepatocellular carcinoma (HCC) in a CD8 T cell-dependent manner." (PMID 31195619, 2019).
hepatocellular carcinoma (continued). "In the future, with the discovery of new immune targets and pathways, such as TIGIT and CD155, combination therapies for hepatocellular carcinoma may achieve further breakthroughs, offering improved clinical treatment benefits." (PMID 41458593, 2025). "Such as in nonsmall cell lung cancer (NSCLC) as well as hepatocellular carcinoma (HCC), a malfunction CD8 + T cell population was discovered to be positively related to high levels of expression of suppressor receptor genes (PD1, PD-L1, LAG3, CTLA4, TIGIT, and HAVCR2)." (PMID 35845137, 2022).